DALRD3 (DALR anticodon binding domain containing 3)
Description:
Involved in tRNA methylation. Facilitates the recognition and targeting of tRNA(Arg)(CCU) and tRNA(Arg)(UCU) substrates for N(3)- methylcytidine modification by METTL2A and METTL2B.
Synonyms: FLJ10496; DEE86; EIEE86
Tractability: PROTAC: ubiquitination databases record sites on it.
Gene: Protein-coding gene on chromosome 3 (49,015,488 to 49,022,293, reverse strand). Ensembl gene ENSG00000178149.
Subcellular location (Human Protein Atlas): Nucleoplasm; Cytosol; Nuclear bodies
Gene Ontology:
Molecular function: protein binding; tRNA binding; aminoacyl-tRNA ligase activity; arginine-tRNA ligase activity; ATP binding; nucleotide binding
Biological process: tRNA C3-cytosine methylation; arginyl-tRNA aminoacylation; gene expression; tRNA aminoacylation for protein translation; tRNA metabolic process
Genetic constraint (gnomAD): Loss-of-function variants: 47 observed, 53.21 expected, observed/expected ratio (o/e) 0.88, 90% interval 0.7 to 1.13. The synonymous counts are far from expectation, so gnomAD's model fits this gene poorly and the ratio says little. Missense variants: 787 observed, 667.79 expected, observed/expected ratio (o/e) 1.18, 90% interval 1.11 to 1.25. Synonymous variants: 347 observed, 281.57 expected, observed/expected ratio (o/e) 1.23, 90% interval 1.13 to 1.35.
Homologues: Orthologues: chimpanzee DALRD3 (99% identical), macaque DALRD3 (95% identical), pig DALRD3 (82% identical), dog DALRD3 (79% identical), mouse Dalrd3 (77% identical), guinea pig DALRD3 (72% identical), rat Dalrd3 (67% identical), rabbit DALRD3 (55% identical), tropical clawed frog dalrd3 (46% identical), zebrafish dalrd3 (40% identical), Drosophila melanogaster CG8097 (16% identical).
Diseases named in the same sentence as DALRD3 in open-access papers:
DALRD3 is named in the same sentence as 12 diseases in open-access papers, as found by Europe PMC text mining. Sharing a sentence is not in itself a finding about the gene and the disease. The quoted sentences say what the papers report.
Epileptic encephalopathy (5 papers, 2020 to 2025). A condition in which epileptiform abnormalities are believed to contribute to the progressive disturbance in cerebral function. "Dysregulation of DALRD3 and subsequent loss of m3C modification in arginine tRNAs have been implicated in severe neurological disorders, such as epileptic encephalopathy." (PMID 38809515, 2024). "The identification of a DALRD3 mutation that abolishes m3C formation in human patients with developmental delay and epileptic encephalopathy has uncovered a physiological link between the m3C modification and neurological function." (PMID 32427860, 2020). "In both patients harboring the DALRD3 mutation, the onset of seizures occurred early in infancy at 6 to 7 months of age indicative of early-onset epileptic encephalopathy." (PMID 32427860, 2020). "Knockdown of a cofactor of METTL2, DALR anticodon binding domain containing 3 (DALRD3), leads to nearly complete loss of m3C32 on cyto-tRNAArg, which might be associated with human developmental delay and epileptic encephalopathy." (PMID 39456272, 2024). "Notably, we identify a homozygous nonsense mutation in the DALRD3 gene that impairs m3C formation in human patients exhibiting developmental delay and early-onset epileptic encephalopathy." (PMID 32427860, 2020). "Here the authors show that DALR anticodon binding domain containing 3 (DALRD3) forms a complex with METTL2 to recognize specific arginine tRNAs and find DALRD3 mutations in patients with developmental delay and early-onset epileptic encephalopathy." (PMID 32427860, 2020). "Remarkably, homozygous nonsense mutations in DALRD3 have been associated with developmental delay and early-onset epileptic encephalopathy, underscoring the critical need for m3C modification in normal brain development." (PMID 39061374, 2024). "Strikingly, we find that DALRD3 is mutated in human patients exhibiting a severe form of epileptic encephalopathy and that these patients no longer exhibit m3C modification in their arginine tRNAs." (PMID 32427860, 2020). "The absence of DALRD3 in human cells, which is crucial for the m3C modification in tRNAArg, results in severe neurological conditions such as early-onset epileptic encephalopathy and pronounced developmental delays." (PMID 39061374, 2024).
insomnia (2 papers, 2020 to 2024). A sleep disorder characterized by difficulty in falling asleep and/or remaining asleep. "The insomnia-associated gene of HEBP2 has shared protein domains with the insomnia-associated gene of TEX264, and TEX264 show evidence of co-expression with DALRD3." (PMID 32830860, 2020). "It has been shown that the expression level of DALRD3 in the brain tissue of patients with insomnia is significantly lower compared to controls, and significant dynamic changes in the expression level of this gene were observed in the mouse cerebral cortex during sleep and sleep deprivation states." (PMID 38425786, 2024). "In conclusion, the current comprehensive study provides multiple lines of evidence for supporting DALRD3, LDHA, HEBP2, TEX264, and FGFR3 as insomnia-associated genes whose abnormal expression level may convey risk to insomnia." (PMID 32830860, 2020). "Furthermore, by conducting a DGE analysis, we found that three genes of DALRD3 (P=5.0 × 10−5), LDHA (P=0.044), and HEBP2 (P=0.032) showed significantly down-regulated expression in insomnia brain samples compared with controls." (PMID 32830860, 2020).
anorexia nervosa (1 paper, 2020). A disorder most often seen in adolescent females characterized by a refusal to maintain a minimally normal body weight, an intense fear of gaining weight, a disturbance in body image, and, in postmenarcheal females, the development of amenorrhea. "While our results cannot be directly compared to past transcriptomic studies of cases and controls, we also mark RPS26 and DALRD3 as key genes in anorexia nervosa." (PMID 32651428, 2020).
breast carcinoma (1 paper, 2013). "We assessed the global change in microRNA expression after estrogen starvation and stimulation in breast cancer cells and identified that miR-191/425 and the host gene DALRD3 are positively associated to ERα-positive tumors." (PMID 23505378, 2013). "Despite the positive correlation between miR-191/425 and the host gene DALRD3 in breast cancer cells, the expression level of the total DALRD3 mRNA was decreased of 35% after 72 h of E2 treatment compared to untreated cells (p-value = 0.053)." (PMID 23505378, 2013). "Finally, a set of 16 different breast cancer cells, clustered by ERα, progesterone receptor (PR) and HER2 expression was also analyzed for the expression of miR-191, miR-425 and the host gene DALRD3." (PMID 23505378, 2013).
colorectal cancer (1 paper, 2018). A primary or metastatic malignant neoplasm that affects the colon or rectum. "Consistent with this suggestion, miR-425-5p is an intronic miRNA embedded within the DALRD3 (DALR anticodon binding domain containing 3 gene) and has been reported to be induced in metastatic gastrointestinal cancers such as gastric and colorectal cancer and possibly associated with melanoma." (PMID 30114287, 2018).
coronary artery disease (1 paper, 2024). "In humans, the DALRD3 gene region has previously been associated with various brain-related traits, educational attainment, and coronary artery disease." (PMID 38255959, 2024).
diabetes (1 paper, 2024). "However, further studies are needed to elucidate the specific mechanisms by which DALRD3 dysregulation and the consequent loss of m3C modification in arginine tRNAs contribute to the pathogenesis of vascular aging in diabetes." (PMID 38809515, 2024). "We used machine learning to identify six key genes closely associated with vascular aging in diabetes: TFB1M, FOXRED2, LY75, DALRD3, PI4K2B, and NDOR1." (PMID 38809515, 2024). "Using bioinformatics and machine learning techniques, we identified six key genes that are closely associated with vascular aging in diabetes: TFB1M, FOXRED2, LY75, DALRD3, PI4K2B, and NDOR1." (PMID 38809515, 2024). "The expression of TFB1M, FOXRED2, DALRD3, PI4K2B, and NDOR1 was negatively correlated with vascular aging in diabetes, while LY75 expression was positively correlated." (PMID 38809515, 2024).
neurological disorders (2 papers, 2020 to 2024). "The loss of arginine tRNA modification due to the DALRD3 mutation provides an avenue to explore additional biological pathways that are key to proper neurological function and perturbed in neurological disorders." (PMID 32427860, 2020). "Due to the emerging links between tRNA modification and neurodevelopmental processes, we next investigated whether DALRD3 is associated with any neurological disorders of unknown genetic etiology." (PMID 32427860, 2020).
tumor (1 paper, 2018). "Among these genes, it is interesting to point out that pathogenic frameshift mutations in DALRD3 were detected in two (out of three) tumor samples." (PMID 29854292, 2018).
DALRD3 also shares sentences with these, for which no sentence is quoted: developmental delay (4 papers); melanoma (1); Onset (1).